EGFR (epidermal growth factor receptor)
Diseases named in the same sentence as EGFR in open-access papers (continued):
Sharing a sentence is not in itself a finding about the gene and the disease.
breast carcinoma (continued). "DDAs are chemically and mechanistically distinct from other classes of anticancer agents and selectively exacerbate the ER stress caused by the aberrantly high expression of EGFR and HER2 that occurs in breast cancers." (PMID 28423644, 2017). "In the T47D ER+ breast cancer cell line ectopic expression of either EGFR or HER2 rendered endogenous HER3 more sensitive to downregulation by the DDA NSC624205, and EGFR overexpression sensitizes EGFR, HER2, and HER3 to RBF3-mediated downregulation." (PMID 28423644, 2017). "Gene dysregulation plays an important role in developing acquired resistance to EGFR-TKIs in breast cancer." (PMID 28288164, 2017). "As such, in both incidence and amenability to ablative therapy, the percentage of patients with oligoprogressive metastatic estrogen receptor positive breast cancer appears significantly lower than that seen in ALK/EGFR positive NSCLC." (PMID 29147583, 2017). "We incubated one healthy and two breast cancer cell lines, each expressing different levels of EGFR, with EGFR-NS, untargeted NS, or unconjugated EGFR antibodies, as well as detectable secondary antibodies." (PMID 28494030, 2017). "Our observation warrants further studies to determine the functional relationship between IKKε and EGFR in breast cancer." (PMID 28532474, 2017). "In bladder and breast cancer, two common receptors are part of the input layer: (i) EGFR and (ii) the retinoic acid receptor alpha (RARA)." (PMID 28775339, 2017). "Preclinical studies have shown that lapatinib inhibits cell proliferation in EGFR and/or ErbB2-overexpressing breast cancer cell lines, even in trastuzumab-resistant cells." (PMID 28938602, 2017). "It was reported that approximately half of TNBC cases exhibit EGFR expression, and EGFR signaling amplification is common in this aggressive form of breast cancer." (PMID 29069872, 2017). "The pretreatment of the breast cancer cell line BT-20 with the EGFR inhibitor erlotinib for at least 4 h dramatically sensitizes the cell line towards doxirubicin induced apoptosis." (PMID 29255142, 2017). "This is in line with previous reports in breast cancer cells where myristoylated AKT prevents the escape of HER3 to EGFR inhibition with gefitinib treatment." (PMID 28032592, 2017). "For example, a recent study showed that in breast cancer cells resistant to the effects of the anti-EGFR/HER2 antibody trastuzumab, IGF-IR induces resistance through the SRC/FAK/FoxM1 signaling." (PMID 27661006, 2017). "The overexpression of miR-675-5p in breast cancer cells lines induced the downregulation of c-Cbl and Cbl-b proteins and increased the stability and the activation of Epidermal growth factor receptor (EGFR) and c-Met." (PMID 29099749, 2017). "We demonstrated that GBP1 expression correlates with EGFR expression (and protein levels) in both tissues and breast cancer cell lines." (PMID 29115931, 2017). "EGFR is a tyrosine kinase receptor in the HER family, which is either overexpressed or mutated in breast cancer cells and is involved in cancer pathogenesis and progression." (PMID 28532474, 2017). "Bioluminescence imaging and H&E staining showed that treatment with agomiR-338-3p, a modified miR-338-3p, which was more stable than miR-338-3p mimics, greatly reduced EGFR-mediated breast cancer lung metastasis." (PMID 28703807, 2017). "Amplification of the EGFR gene is one way to overproduce EGFR, and has been observed in various cancers including breast carcinomas, non-small-cell lung cancer (NSCLC), and glioblastoma multiforme (GBM)." (PMID 28574446, 2017). "Exosomes carrying tumour suppressor microRNA let-7a have been produced that target epidermal growth factor receptor (EGFR)-expressing breast cancer cells following systemic injection and deliver their functional cargo." (PMID 32714581, 2017).
breast carcinoma (continued). "Two basal and one HER2-E human breast cancers harboured outlier EGFR expression, suggesting EGFR remains a potential therapeutic target in a subset of breast cancers that has yet to be fully realized clinically." (PMID 28348404, 2017). "We evaluated the effect of IGF-R and its crosstalk with ERα and EGFR on critical cell properties as well as on the expression and/or localisation of certain syndecans, MMPs and TIMPs in breast cancer cells." (PMID 28079144, 2017). "Throughout all these modification steps, 99mTc-DTPA-can225IgG retained its specificity towards EGFR in solid phase, on the surface of cancer cells in solution as well as in canine mammary carcinoma tissue." (PMID 29137329, 2017). "In contrast, SKBr-3 carries the wild-type of PIK3CA and represents a preclinical model of HER2 gene amplified breast cancer that expresses high levels of EGFR." (PMID 29100381, 2017). "In breast cancer, the dimerization and phosphorylation of epidermal growth factor receptor (EGFR) is increased if it is over-fucosylated, and this lead to the increase of downstream EGFR-signaling, which promotes the malignant behavior and growth of the tumor." (PMID 28977844, 2017). "miR-193a-3p is a novel tumor suppressor that can inhibit cell cycle progression and proliferation in breast cancer by targeting cell cycle network proteins driven by epidermal growth factor receptor (EGFR)." (PMID 29016617, 2017). "For instance, in breast cancer, increased activation of the IGF-1R/PI3K/AKT pathway has been found in an anti-EGFR agents and linked with acquired resistance to anti-EGFR moAbs." (PMID 28002810, 2017). "As neurofibromin activity is a key to regulating the RAS/MAPK pathway, NF1 mutations are important in the acquisition of drug resistance, to BRAF, EGFR inhibitors, tamoxifen and retinoic acid in melanoma, lung and breast cancers and neuroblastoma." (PMID 28637487, 2017). "The data presented here support the novel concept of using PHS in the selective targeting of EGFR signaling for breast cancer cells which highly overexpress EGFR." (PMID 29100426, 2017). "Taken together, these results suggest that EGFR increases breast cancer cell migration and invasion as well as EMT through the miR-338-3p/EYA2 pathway." (PMID 28703807, 2017). "Alcohol stimulated the phosphorylation of EGFR and regulated EGFR signaling in mammary epithelial cells and breast cancer cells." (PMID 29156633, 2017). "By analyzing PHD2 and EGFR expression in TMAs of tumor biopsies from 313 human breast cancer patients, we found that PHD2 showed a positive and significant correlation to EGFR expression (correlation coefficient = 0.231, p<0.001; n=313)." (PMID 28038470, 2017). "Overall, we introduce for the first time the direct crosstalk between the oxygen sensor PHD2 and EGFR-mediated tumorigenesis in breast cancer." (PMID 28038470, 2017). "KLF10 can inhibit breast cancer invasion and metastasis by inhibiting epidermal growth factor receptor (EGFR) transcription and the EGFR signaling pathway." (PMID 28056099, 2017). "Our study describes for the first time a significant positive correlation between PHD2 and EGFR expression in 313 breast cancer patients." (PMID 28038470, 2017). "Upon treatment with EGF, fibroblastic cells or mammary tumor cells overexpressing EGFR and ErbB2 undergo apoptosis in a p38-dependent manner." (PMID 28417908, 2017). "The growth of estrogen-independent breast cancer MDA-MB-468 cells—which overexpress the EGF receptor (EGFR)—is inhibited by EGF; this is accompanied by the increased expression of some genes, including c-myc." (PMID 28417908, 2017). "In an investigation of primary breast carcinomas and normal tissues via immunohistochemical assay, nuclear STAT3 is significantly correlated with EGFR expression in breast cancers." (PMID 27861147, 2017). "Previous studies have demonstrated that administration of EGFR/erbB-2-targeting lapatinib to MMTV-erbB-2 transgenic mice inhibited mammary tumor development." (PMID 28061785, 2017).
breast carcinoma (continued). "In our laboratory we have developed chemical vectors to deliver polyIC to EGFR-overexpressing glioblastoma, breast cancer and vulval carcinoma, as well as HER-2-overexpressing breast cancer." (PMID 28445962, 2017). "Recent work showed that tamoxifen activates the estrogen (G-protein-coupled) receptor (GPER) on breast cancer-associated fibroblasts, promoting proliferation and cell cycle progression through the GPER/EGFR/ERK axis." (PMID 26828520, 2016). "In breast cancer, it has been reported two coupling alternate routes of the E2 synthesis with EGFR signaling." (PMID 26877711, 2016). "Thirty-nine patients treated with anti-EGFR mAbs (trastuzumab for advanced breast cancer, or cetuximab for advanced colorectal or advanced head and neck cancer) were included in the study." (PMID 27994592, 2016). "GS-Rg3 reduced the expressions of EGFR and pEGFR in MCF-7 breast cancer cells in a dose-dependent manner, suggesting that GS-Rg3 inhibits the tumor growth by targeting EGFR and its down- stream signal transduction pathways." (PMID 28119606, 2016). "Evidence from breast cancer shows that ANO1 is involved in oncogenic signaling by activating EGFR and CAMK pathways to promote cancer progression." (PMID 27732935, 2016). "To further investigate the anti-tumor activities mediated by EGFR downregulation in breast cancer cells, we examined the expression of c-myc and Nanog in MCF7 cells after co-treatment with tamoxifen and DCA." (PMID 27494858, 2016). "Our results suggest possible distinct interactions and co-activation patterns of EGFR and cMET among the subgroups of breast cancer." (PMID 27055285, 2016). "Overexpression or activation of EGFR in mesenchymal and stem-cell featured breast cancer, such as MDA-MB-231 cell lines has recently been identified as a highly predictive marker for poor clinical outcomes." (PMID 27829223, 2016). "It has previously been shown in breast carcinoma cell lines that inhibition of SRC family kinases prevents the phosphorylation of MAPK induced by stimulation of EGFR." (PMID 26788073, 2016). "In the neoadjuvant setting postmenopausal patients with EGFR-positive, and ERα-positive breast cancer were randomized for gefitinib (EGFR tyrosine kinase inhibitor) alone or gefitinib plus anastrazole, an aromatase inhibitor." (PMID 27129152, 2016). "This uncontrolled EGFR signaling triggers breast cancer cells to escape from a primary tumor and spread to the lung, resulting in a poor prognosis for the disease progression." (PMID 27142862, 2016). "We also successfully used electroporation to load miRNA into exosomes targeted to the epidermal growth factor receptor (EGFR) of breast cancer cells." (PMID 26861303, 2016). "Because the majority of erbB2-overexpressing (erbB2-positive) breast cancer cells express little or basal levels of EGFR, lapatinib mainly inhibits erbB2 kinase activity (intracellular domain) in erbB2-positive breast cancers." (PMID 26621843, 2016). "In breast cancer, EGFR activation induced FOXC1 transcription and FOXC1 knockdown impaired cell proliferation and migration." (PMID 26198045, 2016). "Here, we found that the blockade of PDK activity by an inhibitor or silencing decreased total cellular EGFR levels in tamoxifen-treated breast cancer cells." (PMID 27494858, 2016). "STAT3 binds to and significantly activates theTWIST promoter in cooperation with EGF receptor(EGFR) in human breast cancer cells." (PMID 26862521, 2016). "Recently, YB-1, an oncogenic transcription/translation factor, was shown to regulate EGFR transcription in breast cancer." (PMID 27713156, 2016). "Considering the importance of β1 in cell survival and cell migration, a combination treatment with anti-EGFR and anti-β1 drugs is recommended as a very useful therapy for breast cancer." (PMID 26728650, 2016). "EGFR interacts with HER2 and high-level expression of EGFR attenuates the effect of anti-HER2-directed antibodies in HER2-amplified breast cancer cells." (PMID 26863629, 2016).
breast carcinoma (continued). "To explore a possible relationship between EGFR and NeuGcGM3 in cancer, we first evaluate their expression in two models of spontaneous lung metastasis in mice: Lewis lung carcinoma (3LL-D122) and mammary carcinoma (4T1)." (PMID 27449755, 2016). "Unfortunately, several clinical tests demonstrated a poor response of breast cancer patients to EGFR-TKI." (PMID 27590506, 2016). "In summary, we demonstrate for the first time that EA synergistically augments the antitumor effects of irreversible EGFR TKIs in breast cancer." (PMID 27487128, 2016). "In breast cancer, miR‐133a regulated cell cycle and proliferation by targeting EGFR through EGFR/Akt pathway." (PMID 27465833, 2016). "EGFR mutations and ERBB2 overexpression are well known mechanisms that lead to constitutive activation of ERBB signaling pathways in lung and breast carcinoma." (PMID 26745281, 2016). "HSP90 interacts with a variety of proteins that play important roles in breast cancer including receptor tyrosine kinases such as EGFR and HER2 as well as RAF and AKT." (PMID 27129177, 2016). "Analogous to these previous studies, our results showed a synergistic effect of EA with irreversible EGFR TKIs in breast cancer." (PMID 27487128, 2016). "Activation and over-expression of EGFR play significant roles in the invasion and metastasis cascade of breast cancer." (PMID 27683033, 2016). "The dual-targeting TKI Lapatinib, which inhibits both EGFR and ErbB2, is approved for use in ErbB2 positive breast cancer upon relapse following treatment standard chemotherapy and trastuzumab." (PMID 27597943, 2016). "EGFR mutation or ErbB2 overexpression has been viewed as critical biomarkers for treatment of EGFR TKIs in NSCLC and breast cancer patients." (PMID 26595522, 2016). "EGFR amplification in breast carcinomas and lung adenocarcinoma are also example of neoplasam involving such RTKs gene amplification." (PMID 27051190, 2016). "According to previous research, overexpression of EGFR, ERBB2, and ERBB3 is associated with poor prognosis and negatively correlated with estrogen receptor (ER) expression in breast cancer." (PMID 26907936, 2016). "We found that a safe dose of EA extends the therapeutic effect of irreversible EGFR TKIs on breast cancer." (PMID 27487128, 2016). "Although tamoxifen treatment decreased EGFR levels slightly in MCF7 and T47D cells, no significant increase in cell death was observed in the cells, suggesting that a critical level of EGFR is needed for the survival of breast cancer cells." (PMID 27494858, 2016). "The Kindlin-2/integrin β1/AKT axis was shown to contribute to esophageal squamous cell cancer, while the Kindlin-2/EGFR/AKT axis was shown to be involved in breast cancer." (PMID 27713156, 2016). "~15–25% of breast cancer patients overexpress the human epidermal growth factor receptor (EGFR) family member HER2." (PMID 27045589, 2016). "AGO2 phosphorylation mediated EGFR-enhanced cell survival and invasiveness under hypoxia, and was correlated with poorer overall survival in breast cancer patients." (PMID 26646588, 2016). "Previously, we showed that tyrosine phosphorylation (Tyr774) of the adaptor protein c-CBL located downstream of EGFR in the ubiquitination cascade was slightly increased in breast cancer cells shortly after exposure to compound NSC." (PMID 27187356, 2016). "Taken together, these results indicate that E1A reduces AXL expression and consequently results in enhanced EGFR-TKI sensitization of breast cancer cells both in vitro and in vivo." (PMID 27590506, 2016). "A genetically engineered Pseudomonas aeruginosa strain that expresses type 1 fimbriae can specifically adhere to breast cancer cells overexpressing the EGFR and block the EGFR signaling pathway." (PMID 27406561, 2016). "In breast cancer cells, lipid rafts provide a platform for the interaction of EGFR and c-Src, leading to activation of cellular survival signaling." (PMID 26918609, 2016).
breast carcinoma (continued). "Serum-starved ERBB2-positive SKBr3 breast cancer cells were exposed to EGF or heregulin (HRG) to activate HER2 through EGFR/HER2 and HER2/HER3 signalling routes, respectively." (PMID 27402251, 2016). "Recently, we have described a new class of nitro-benzoxadiazole derivatives, which activate EGFR and thereby trigger downstream signaling circuits in the cytoplasm and apparently in the nucleus of breast cancer cells." (PMID 27187356, 2016). "The protein expression levels of EGFR on cells of the human mammary carcinoma cell lines MDA-MB-231 and MDA-468 as well as of the human epidermoid carcinoma cell line A431 were investigated by Western blotting." (PMID 26912069, 2016). "The most widely accepted method in clinical practice is through identification of significant immunohistochemistry (IHC) surrogates for basal-like breast cancer, e.g. epidermal growth factor receptor (EGFR) and basal cytokeratins (CK5/6)." (PMID 26930401, 2016). "The success of trastuzumab in HER2+ breast cancer and EGFR inhibition with gefitinib or erlotinib in NSCLC demonstrate the promise of TKI treatment." (PMID 27655711, 2016). "Lapatinib was approved for the treatment of breast cancer due to the correlation between the EGFR and HER-2 signaling and the poor prognosis." (PMID 27756261, 2016). "Protopine has been found to impair the cancer cell invasion and metastatic potential of MDA-MB-231 breast cancer cells by reducing the expression of adhesion molecules such as epidermal growth factor receptor (EGFR), ICAM-1 and integrins." (PMID 27618894, 2016). "In summary, our results suggest that DCA is an attractive potential drug that sensitizes cells to tamoxifen-induced cell death and overcome tamoxifen resistance via downregulation of EGFR expression in breast cancer cells." (PMID 27494858, 2016). "Binding of EGF to its cognate epidermal growth factor receptor (EGFR) family has been shown to stimulate EMT in breast cancer cells, leading to altered expression of E-cadherin and vimentin." (PMID 27253373, 2016). "We showed that DCA enhanced the cytotoxicity of tamoxifen to breast cancer cells by inhibiting EGFR expression." (PMID 27494858, 2016). "It is their inappropriate expression that inextricably links these proteins to a malignant phenotype, and it is universally accepted that EGFR, HER2 and ER are unambiguously linked to the breast cancer cell." (PMID 27768738, 2016). "Most breast cancers that become resistant to endocrine therapy have an increased expression of EGFR with activation of downstream signaling pathways." (PMID 27564112, 2016). "Since HIF2α is reported to induce EGFR protein levels under hypoxic conditions in renal epithelial cells, we tested the effect of HIF2α downregulation by siRNA on EGFR protein levels in antiestrogen-resistant breast cancer cells." (PMID 26849233, 2016). "Our study emphasizes the importance of PI3K/PTEN pathway activity in ER-negative and basal-like breast cancer and supports the future clinical evaluation of combining EGFR and PI3K pathway inhibitors for the treatment of BLBC." (PMID 27484095, 2016). "The combination therapeutic effects of EA with irreversible EGFR TKIs in breast cancer are worthy of clinical evaluation in humans." (PMID 27487128, 2016). "Irina Daurkin and colleagues reported that TAMs regulate murine breast cancer stem cells through a novel paracrine EGFR/Stat3/Sox-2 signaling pathway." (PMID 27703219, 2016). "Ternary complex formation among CDCP1, EGFR, and Src is paralleled by disruption of cell-cell and cell-substratum adhesion in human breast carcinoma cells, coincident with relocalization of E-cadherin from cell-cell junctions to cytoplasmic vesicles." (PMID 27495374, 2016). "We found that irreversible EGFR TKIs and EA synergistically inhibit breast cancer both in vitro and in vivo." (PMID 27487128, 2016). "We conclude that EA synergistically enhances the antitumor effects of irreversible EGFR TKIs in breast cancer." (PMID 27487128, 2016).